AKR1C1 (aldo-keto reductase family 1 member C1)
Diseases named in the same sentence as AKR1C1 in open-access papers (continued):
Sharing a sentence is not in itself a finding about the gene and the disease.
metastatic melanoma (2 papers, 2024). A melanoma that has spread from its primary site to another anatomic site. "Indeed, we recently identified three members of the aldo-keto reductase family of enzymes (AKR1C1–3), responsible for metastatic melanoma resistance to ferroptosis execution." (PMID 38368399, 2024). "We previously demonstrated that the AKR1C1 closely related C2 and C3 members of the AKR superfamily are co-responsible for the resistance of metastatic melanoma to ferroptosis execution." (PMID 39671850, 2024).
metastatic tumors (2 papers, 2016 to 2022). "The immunohistochemical assay showed that the expression level of the AKR1C1 protein in metastatic tumors was significantly elevated compared to the corresponding primary tumors, suggesting that higher AKR1C1 expression is associated with metastasis in NSCLC." (PMID 35370661, 2022). "RT-PCR analysis demonstrated that the metastatic tumors exhibited higher levels of AKR1C1 mRNA compared with the primary sites (P = 0.008)." (PMID 27698389, 2016). "The expression levels of the AKR1C1 protein were also elevated in the metastatic tumors, particularly in UM-UC-3-liver and UM-UC-3-bone cells." (PMID 27698389, 2016).
osteosarcoma (2 papers, 2021 to 2025). A usually aggressive malignant bone-forming mesenchymal neoplasm, predominantly affecting adolescents and young adults. "Research indicates that AKR1C1 is overexpressed in osteosarcoma (OS) and correlates with poor prognosis in OS patients." (PMID 39964621, 2025). "Our recent study suggested that AKR1C1 is a novel target of FoxM1 and FoxM1/AKR1C1 signaling is inhibited by avasimibe at osteosarcoma." (PMID 34127944, 2021).
sarcoidosis (2 papers, 2020 to 2023). Sarcoidosis is a multisystemic disorder of unknown cause characterized by the formation of immune granulomas in involved organs. "According to Gini score calculated from gene expression values, we examined the top-6 most important AA metabolism-related genes (including PLA2G6, PLA2G7, AKR1C1, AKR1C3, LTA4H, and PTGER4) in sarcoidosis, whose expression showed a positive correlation with sarcoidosis samples." (PMID 33097805, 2020).
squamous carcinoma (2 papers, 2015 to 2020). "Low AKR1C1 expression was more frequently observed in undifferentiated non‐keratinized carcinoma (UDC), T3‐T4, N2‐N3, M1 and stage III‐IV tumours than in differentiated non‐keratinized squamous carcinoma (DNKC), T1‐T2, N0‐N1, M0 and stage I‐II tumours." (PMID 32307891, 2020). "For AKR1C1 RNA, higher expression levels in tumor tissues were seen in squamous cell carcinoma (10.530 versus 9.525, P = 0.0013) but not adenocarcinoma." (PMID 26338969, 2015).
acute lymphoblastic leukemia (1 paper, 2020). Leukemia with an acute onset, characterized by the presence of lymphoblasts in the bone marrow and the peripheral blood. "On the other hand, the NRF2-driven overexpression of aldo keto reductase 1C (AKR1C1) enzymes has been associated with therapy resistance in T-cell acute lymphoblastic leukemia (T-ALL) and their genetic or pharmacologic inhibition to enhance the efficacy of vincristine treatment." (PMID 32443774, 2020).
astroglioma (1 paper, 2022). "AKR1C1 and AKR1C3 are members of the AKR superfamily which has been previously shown to be associated with oncogenic potential and proliferation capacity, and selective targeting of AKR1C proteins in GBM could delay the acquisition of resistance to TMZ of astroglioma cells." (PMID 35359663, 2022).
autoimmune thyroid disease (1 paper, 2024). Inflammatory disease of the thyroid gland due to autoimmune responses leading to lymphocytic infiltration of the gland. "The involvement of AKR1C1 was demonstrated in vesicular transport snare interactions, autoimmune thyroid disease, and olfactory transduction pathways." (PMID 38517368, 2024).
bladder tumors (1 paper, 2016). "The AKR1C1 expression level in primary bladder tumors was elevated 2.4-fold compared to that in control cells." (PMID 27698389, 2016).
colitis (1 paper, 2022). Inflammation of the colon. "In addition, western blotting results revealed multiple functions of RSBDP in the DSS-induced colitis which were exerted by anti-inflammatory and pro-apoptotic activities, relying on the AhR/CYP1B1 and AKR1C1/PI3K/AKT pathways." (PMID 36145261, 2022).
colorectal adenocarcinoma (1 paper, 2017). The most common type of colorectal carcinoma. "Conversely, nontoxic doses of SFN (50 μM) caused an increase in the catalytic activity, protein and mRNA levels of AKR1C1 in human colorectal adenocarcinoma Caco-2 cells." (PMID 29144397, 2017).
colorectal tumours (1 paper, 2022). "An interesting corollary of our study is the unexpected downregulation of AKR1B10 and AKR1C1 expression in human colorectal tumours." (PMID 35204145, 2022).
diabetes (1 paper, 2020). "Since the prostate tissue of patients with T2D AKR1C1, C2, and C3 transcripts showed positive associations with proliferative, HIF1α, and NFκB genes, our results suggest that in the prostate gland, AKR1C enzymes could be involved in the induction of inflammatory processes induced by diabetes." (PMID 32932589, 2020). "The mRNA level of AKR1C1 was significantly higher in PCa of the T2D group than in patients without diabetes." (PMID 32932589, 2020). "In the prostate tissue of patients with T2D, AKR1C1 and AKR1C2 transcripts were higher compared to samples of patients without diabetes." (PMID 32932589, 2020). "We observed that the gene expression levels of AKR1C1 and C2 had increased significantly and that the AKR1C3 mRNA level tended to be higher in the prostate tissue of patients with T2D than in samples of patients without diabetes." (PMID 32932589, 2020).
endometrial adenocarcinoma (1 paper, 2022). "In addition, knockdown of MGLL can sensitize endometrial adenocarcinoma cells to progesterone, possibly by affecting ROS generation and reducing the expression of AKR1C1." (PMID 36550099, 2022).
epilepsy (1 paper, 2022). A brain disorder characterized by episodes of abnormally increased neuronal discharge resulting in transient episodes of sensory or motor neurological dysfunction, or psychic dysfunction. "AKR1C1-3 seems to be key in the pathophysiology of PCDH19-related epilepsy." (PMID 35822151, 2022).
gallstones (1 paper, 2023). Solid crystalline precipitates in the biliary tract, usually formed in the gallbladder, resulting in the condition of cholelithiasis. "Additionally, the downregulated proteins in gallstone bile showed enrichment in bile acid and bile salt transport (padjusted = 0.004), which included AKR1C1, ABCC2, ABCB11, and ATP8B1." (PMID 38111640, 2023).
glaucoma (1 paper, 2023). Increased pressure in the eyeball due to obstruction of the outflow of aqueous humor. "We found that glaucoma LC cells exhibit a significant increase in malondialdehyde (MDA) and reduced antioxidants such as aldo-keto reductase family 1 member C1 (AKR1C1) and glutamate—cysteine ligase catalytic subunit (GCLC)." (PMID 36674805, 2023).
hilar cholangiocarcinoma (1 paper, 2021). A cholangiocarcinoma that arises from the junction, or adjacent to the junction, of the right and left hepatic ducts. "Univariate and multivariate analysis of overall survival in 49 patients with hilar cholangiocarcinoma according to clinicopathological factors and AKR1C1 overexpression." (PMID 34127944, 2021). "Univariate and multivariate analysis of time to progression in 49 patients with hilar cholangiocarcinoma according to clinicopathologic factors and AKR1C1 overexpression." (PMID 34127944, 2021).
Hyperglycemia (1 paper, 2020). An increased concentration of glucose in the blood. "Hyperglycemia was indeed found to induce the mRNA levels of AKR1C1, AKR1C2, and AKR1C3." (PMID 32932589, 2020).
nasopharyngeal carcinoma (1 paper, 2020). A carcinoma arising from the nasopharyngeal epithelium. "However, the expression and role of AKR1C1 in nasopharyngeal carcinoma has not been reported so far." (PMID 32307891, 2020).
oral carcinoma (1 paper, 2017). "Cigarette smoke has been shown to induce cytochrome P450 (CYP1A1, CYP1B1) and aldo-keto reductase (AKR1C1, AKR1C3, AKR1B10) genes in oral dysplasia and primary oral carcinoma cell lines." (PMID 28467356, 2017).
oropharyngeal cancer (1 paper, 2025). Carcinoma, predominantly squamous cell, arising from the epithelial cells of the oropharynx. "In relation to oral and oropharyngeal cancer, significant associations were observed for a suite of genes including HSPA5, TNFAIP6, AKR1C1, CASP1, ANXA1, and MYC." (PMID 41023518, 2025).
oropharyngeal squamous cell carcinoma (1 paper, 2023). "Upregulated AKR1C1 expression was found in HPV16-positive oropharyngeal squamous cell carcinoma with viral integration, and it was linked with a poor prognosis in both HPV-positive and HPV-negative tumors." (PMID 36936948, 2023).
ovarian endometriosis (1 paper, 2015). A non-neoplastic disorder characterized by the growth of endometrial tissue in the ovaries. "AKR1C1 is family member of the Aldo-keto reductases, and have been reported to enhance progesterone metabolism in ovarian endometriosis." (PMID 25889687, 2015).
ovarian tumor (1 paper, 2025). "There was evidence indicating that the decrease of AKR1C1 and AKR1D1 played an important role in the formation of ovarian tumor tissues and inflammation." (PMID 40370520, 2025).
renal carcinoma (1 paper, 2017). A carcinoma arising from the epithelium of the renal parenchyma or the renal pelvis. "Increased expression of proteins involved in sex steroid inactivation (AKR1C1, AKR1C2, AKR1C3, AKR1B10) in DIO1 re-expressing renal cancer cells might indicate decreased local production of androgens, which have been linked to proliferation of renal and other cancers expressing androgen receptor." (PMID 29272308, 2017).
renal tumors (1 paper, 2017). "Specifically, the transcript expressions of AKR1C1, S100A2, PLAU, SLC3A2, TBC1D2, and WIZ were decreased, while expressions of TGM2, SLC7A5, and NMI were increased in renal tumors when compared with non-tumorous control samples." (PMID 29272308, 2017).
schizophrenia (1 paper, 2024). A major psychotic disorder characterized by abnormalities in the perception or expression of reality. "Of the 19 molar ratios that may reflect a balance between AKR1C1 and HSD17B2, 3 are lower, 11 are not significantly different, and 5 are higher in patients compared with controls (p = 0.494, Mann–Whitney test), suggesting the absence of a significant trend in relation to schizophrenia." (PMID 39201417, 2024).
serous ovarian cancer (1 paper, 2022). "While AKR1C1/2 is expressed in low grade as well as high grade serous ovarian cancer at the same level, endometrioid G3 carcinomas show lower expression levels than G1." (PMID 35115586, 2022).
cancer (66 papers, 2007 to 2025). A tumor composed of atypical neoplastic, often pleomorphic cells that invade other tissues. "AKR1C1 and 1C3 have already been implicated in therapeutic resistance via the mediation of intracellular ROS levels for several types of cancer." (PMID 34830394, 2021). "Further research showed that AKR1C1 was related with many pathways involved in the process of ferroptosis and associated with diverse cancer-infiltrating immune cells." (PMID 34702254, 2021). "AKR1C1 is a member of the human aldo-keto reductase family associated with the occurrence of various cancers." (PMID 34938341, 2021). "Decreased invasion caused by AKR1C1 knockdown suggests a novel role of AKR1C1 in cancer invasion, which is probably due to the regulation of Rac1, Src, or Akt." (PMID 27698389, 2016). "Overexpression of AKR1C1 is associated with cancer progression." (PMID 36263088, 2022). "AKR1C1 has been confirmed as a biomarker of cancer-associated fibroblasts in TME." (PMID 34030694, 2021). "Our findings suggest that overexpression of Nrf2 and AKR1C1 in endometrial precancer/cancer may be part of the molecular mechanisms underlying progestin resistance." (PMID 26824415, 2016). "AKR1C1 encodes a drug-metabolizing enzyme; the level of expression of this gene may influence the prognosis of different cancers." (PMID 25182732, 2014). "In addition to endogenous substrates, AKR1C1 and 1C2 have been implicated in metabolism of various exogenous substrates, including drugs (e.g., cancer chemotherapeutics), carcinogens (e.g., polycyclic aromatic hydrocarbon, aflatoxin dialdehyde), and reactive aldehydes such as 4HNE." (PMID 23766854, 2013). "IHC staining showed that malignant tumors with high TSPO expression had significantly higher AKR1C1 and FTH1 expression levels." (PMID 40842566, 2025). "Strikingly, in vivo, AKR1C1 depletion renders cancer cells more sensitive to ferroptosis and synergizes with ferroptosis inducers to suppress tumor growth much more potently than either treatment alone." (PMID 39478199, 2025). "AKR1C1+ inflammatory fibroblast significantly co-localized with cancer cells, neutrophil, CTSK+ macrophage, DC1, and PRR-induced mo-DC." (PMID 38744958, 2024). "Compared to TN and MPR patients, we observed that enzymes in the Aldo-Keto Reductase family (AKR1B1/10 and AKR1C1-3) were highly expressed in cancer cells from NMPR patients." (PMID 36869384, 2023). "AKR1C1, CYP27A1, CYP2C9, GLB1, HMGCS2, and PLPP1, all six LMRGs, have been implicated in the genesis and progression of cancer." (PMID 36936948, 2023). "AKR1C1 regulates the metabolism of progesterone and is closely related to the progression of malignant tumors." (PMID 35370661, 2022). "All these results suggest that AKR1C1 plays a complex role in carcinogenesis and represents an important target for cancer therapy." (PMID 35370661, 2022). "Aldo-keto reductase family 1 member C1 (AKR1C1) plays an important role in cancer cell proliferation and metastasis, and has gained attention as an anticancer drug target." (PMID 35370661, 2022). "The expression of AKR1C1-4 commonly is correlated with a poor prognostic in patients with different types of cancer." (PMID 35563388, 2022). "We found that the overall survival time of patients with high levels of AKR1C1 was cut down compared with patients with low levels of AKR1C1 (p = 0.0092) by the Kaplan–Meier analysis, suggesting the specific role of AKR1C1 in cancer metastasis." (PMID 35370661, 2022). "An upregulation of AKR1C1/2 enzymes was seen especially in hormone dependent cancer types, including prostate or endometrial carcinoma." (PMID 35115586, 2022). "The expression level of AKR1C1 in tumor and corresponding normal tissues in cancer was verified on Oncomine database." (PMID 34702254, 2021). "Meanwhile, the FoxM1/AKR1C1 axis in human cancers was the potential target of avasimibe which successfully retarded cell proliferation and tumor growth of CCA." (PMID 34127944, 2021).
cancer (continued). "Our results showed the inhibitory effect of avasimibe on CCA in vivo and in vitro and demonstrated that avasimibe targets FoxM1/AKR1C1 signaling, an essential pathway in tumorigenesis and cancer progression." (PMID 34127944, 2021). "Our present study extends the understanding of the role of SIRT2 in cancer by identifying its downregulating effect on the metastasis potential of NSCLC cells with high expression level of AKR1C1." (PMID 32104503, 2020). "Even if the expression pattern of AKR1C1 and C2 is influenced by the cancer state (primary PCa vs. advanced CRPCa), the molecular mechanism behind this difference has not yet been elucidated." (PMID 32932589, 2020). "Previous studies have identified AKR1C1 as a key driver promoting malignancy in various cancers 12-16." (PMID 32104503, 2020). "AKR1C1, C2, and C3 proteins regulate steroid hormone signaling and play a key role in cancer growth, metastasis, and apoptosis." (PMID 32932589, 2020). "Actually, cumulative data indicated that AKR1C1 plays an important role in chemotherapy resistance in several cancers." (PMID 32307891, 2020). "In this study, we found AKR1C1 contributing to cisplatin-resistance and cancer stemness phenotype in HNSCC." (PMID 31182137, 2019). "AKR1C1 expression is a poor prognostic marker in a wide variety of cancers, including breast, prostate, non-small cell lung, and esophagus, and it is upregulated in recurrent tumors and cancer stem cells." (PMID 31182137, 2019). "In accordance with the results of cancer cell analysis, this experiment revealed diminished expression of AKR1C1 (FC=1.6-2.4) and ALDH1A1 mRNAs (FC=1.7), as well as upregulation of ALDH1A3 mRNA in xenograft tumors (FC=1.7-4.0)." (PMID 31413744, 2019). "AKR1C1, STATs, and cytokine IL-6 potentially form a positive feedback loop in cancer to enhance cisplatin-resistance." (PMID 31182137, 2019). "The correlation of high AKR1C1 expression with cancer is supported by two recently studies, possibly due to the ability of AKR1C1 to act as tumor suppressor gene." (PMID 27188717, 2016). "One of the metabolic enzymes, aldo-keto reductase 1C1 (AKR1C1), plays an essential role in cancer invasion/metastasis and chemoresistance." (PMID 27698389, 2016). "To further investigate how Nrf2 and AKR1C1 contribute to endometrial precancer/cancer progestin resistance, we performed the mechanism related experiments in vitro." (PMID 26824415, 2016). "In summary, we have in this study demonstrated for the first time that Nrf2 and AKR1C1 overexpression is likely one of the main molecular mediators of progestin resistance in patients with endometrial precancers and well differentiated carcinomas." (PMID 26824415, 2016). "Aldo-keto reductases overexpressed in our cancer dataset (AKR1C1, AKR1B10, and AKR1C3) are involved in the reduction of retinal to retinol." (PMID 25243088, 2014). "Increased expression of AKR1C1 gene was observed in various cancer cells including lung, liver and ovarian." (PMID 24003325, 2013). "Since AKR1C1 was previously demonstrated to be highly related to ferroptosis in some cancer cells, we sought to determine whether AKR1C1 depletion could affect ferroptosis in ECC cells." (PMID 39478199, 2025). "Finally, in a xenograft mouse model of ECC, AKR1C1 depletion sensitizes cancer cells to ferroptosis and synergizes with ferroptosis inducers to suppress tumor growth." (PMID 39478199, 2025). "Importantly, AKR1C1 is suggested to be a potential therapeutic target to promote cancer cell death under various contexts." (PMID 39478199, 2025). "Notably, in an ECC xenograft mouse model, AKR1C1 depletion sensitizes cancer cells to ferroptosis and synergizes with ferroptosis inducers to suppress tumor growth." (PMID 39478199, 2025). "AKR1C1 staining was predominantly found in the cytoplasm of cancer cells in xenograft tumors." (PMID 38472205, 2024).